FOXO1 (forkhead box O1)
Diseases named in the same sentence as FOXO1 in open-access papers (continued):
Sharing a sentence is not in itself a finding about the gene and the disease.
Insulin resistance (continued). "We found that MOL supplementation markedly decreased the body weight, significantly upregulated the expression of Sirt1, FoxO1, PGC‐1α, IGF1, and substantially modulated the sex hormone level and improved insulin resistance, which may be associated with the relieves oxidative stress." (PMID 37701184, 2023). "The occurrence of diabetes can lead to a decrease in SIRT1 activity and its expression, and then the enhanced acetylation of FOXO1 will lead to a significant increase in blood glucose in vivo after FOXO1 activation, which may ultimately aggravate insulin resistance." (PMID 35739982, 2022). "However, whether VD deficiency affects gluconeogenesis and insulin resistance in the liver through regulating Sirt1 expression and AKT/FOXO1 signaling remains unclear." (PMID 35132380, 2022). "In a study on skeletal muscle-specific VDR-null mice, the mice were found to develop insulin resistance and glucose intolerance with elevated FoxO1 expression and activity, which might be responsible for insulin resistance and impaired glucose metabolism in the skeletal muscle." (PMID 35859985, 2022). "Thus, it can be concluded that impaired VD signaling may induce hepatic gluconeogenesis and hepatic insulin resistance through attenuating the activity of the AKT/FOXO1 axis." (PMID 35132380, 2022). "However, little is known about the relationship between FOXO1 and insulin resistance in PCOS." (PMID 34637688, 2021). "Thus, increased insulin signalling in early diabetes, prior to the development of glomerular insulin resistance, may suppress FoxO1 activity and IGFBP-1 expression in the glomerulus and associated signalling." (PMID 33758952, 2021). "Moreover, FOXO1 could promote the production of IL-1β in macrophages and contribute to insulin resistance." (PMID 34637688, 2021). "The DEGs Slc27a1, Cpt1a, Srebf1, and Foxo1 were enriched in insulin resistance pathway and also appeared in the network of top 10 upregulated and downregulated mRNAs, indicating these four mRNAs might play key roles in the development of hyperglycemia and T2D in GK rats at the age of 3 and 4 weeks." (PMID 32095365, 2020). "Thus, in the presence of insulin resistance as in GK rats, the impaired ability of insulin to deactivate FOXO1 may have enhanced fatty acid utilization." (PMID 32612543, 2020). "It has been shown, that under pathophysiological conditions such insulin resistance and metabolic dysfunction FoxO1 expression may help drive the expression of genes involved in combating oxidative stress and that there is interplay between SirT1 and FoxO in ROS reduction." (PMID 33344504, 2020). "In order to verify if the altered mTOR and FoxO1 pathways could contribute to skeletal muscle atrophy in DM and T2DM patients i.e. those patients who showed insulin resistance, we analysed the correlation of mTOR, FoxO1, MuRF1 and Atrogin-1/MAFbx expressions with atrophy factors." (PMID 30901379, 2019). "In addition, the low expression levels of FOXO1 suggested it may activate insulin production and insulin resistance signaling to enhance glucose and lipid metabolism in the liver." (PMID 31456815, 2019). "Thus, there must be a tight cross-regulation C/EBP-α, FOXO1 and PPAR-γ2 that modulates adipogenesis linked to insulin resistance in an alternative insulin pathway and common alternative pathway, since it has been reported that they physically interact, cooperate and activate each other." (PMID 31547433, 2019). "Additionally, due to the effect of RSV on SIRT1 activity, it can be concluded that RSV might have a beneficial effect on FOXO1, and FOXO3a expression in adipose tissue, and might consequently improve the oxidative stress and insulin resistance." (PMID 31565649, 2018). "Therefore, it could be hypothesized that RSV by exerting a beneficial effect on FOXO1 expression resulted in decreasing blood glucose level, improving subsequent oxidative stress and ameliorating insulin resistance." (PMID 31565649, 2018).
Insulin resistance (continued). "Thus, FOXO1 indirectly might induce an inflammatory status of the adipose tissue, responsible for the insulin resistance in type 2 diabetes." (PMID 32309538, 2013). "Specifically, we will explore how anthocyanins influence key downstream targets of the PI3K/Akt signaling pathway, including FOXO1, GSK3β, GLUT4, and mTOR, as well as their role in reducing oxidative stress, inflammation, and insulin resistance." (PMID 40218884, 2025). "Upon insulin resistance, AKT-mediated FOXO1 inactivation is attenuated, and FOXO1 activity is augmented." (PMID 40760121, 2025). "TOX3 overexpression activates the gluconeogenic program, resulting in hyperglycemia and insulin resistance in mice and hepatocyte-specific TOX3 knockout suppresses gluconeogenesis through FOXO1." (PMID 40218365, 2025). "Reduces inflammation, improves gut microflora, alleviates insulin resistance (PI3K/AKT/GLUT4, FOXO1), reduces inflammatory markers, promotes muscle growth (MyHC, Sirt1, PGC-1α, MEF2C, AMPK)." (PMID 41404330, 2025). "Specifically, regarding genes related to insulin resistance pathway, we highlight SOCS3, GSK3B, STAT3, PTEN, TRIB3, FOXO1, and PTPRF, along with MAPK8, which plays a role in metabolic stress and inflammation." (PMID 41282288, 2025). "FoxO1 serves as an AKT-mediated substrate in the PI3K/AKT signaling pathway, and its activation correlates with insulin resistance and hyperglycemia." (PMID 41001671, 2025). "Moreover, miR-223 plays a role in minimizing liver inflammation by targeting neutrophils and may offer a mechanism for controlling liver damage and miR-223 impairs the compensatory response of β-cells to high-fat-diet-induced insulin resistance by directly targeting FOXO1." (PMID 40668532, 2025). "FOXO1 mediates the progression of MAFLD by regulating glucose metabolism, lipid metabolism, insulin resistance, oxidative stress, hepatic fibrosis, hepatocyte autophagy, apoptosis, and immune inflammation." (PMID 39021599, 2024). "Meanwhile, FoxO1‐dependent downregulation of IRS1 led to reduced AKT signalling and insulin resistance." (PMID 38494853, 2024). "Functional enrichment analysis showed that SOCS3, IL6, FOXO1, CEBPB, SOX9, and PPARGC1A were mainly involved in the adipocytokine signaling pathway, insulin resistance, FoxO signaling pathway, AMPK signaling pathway, and PI3K-Akt signaling pathway." (PMID 38415055, 2024). "Knockout of SARM1 in mice leads to a significant activation of insulin resistance-related pathways including AKT, GSK3β, IRS1, and FOXO1, thereby alleviating insulin resistance in mice fed a high-fat diet." (PMID 39021599, 2024). "The insulin receptor INSR is one of the downstream target genes of FoxO1 and is upregulated through PERK activation, inducing cellular insulin resistance." (PMID 36830968, 2023). "TMAO binds to PERK, leading to increased FOXO1 activity and activation of the AKT signaling pathway, resulting in insulin resistance and diabetes." (PMID 37600034, 2023). "In this state of advanced insulin resistance, the decrease in insulin lowers PI3K/AKT signaling and increases FoxO1 activity which impairs PDX1-mediated β-cell growth further reducing insulin secretion and contributing to T2D pathogenesis." (PMID 37941908, 2023). "PCOS patients generally have insulin resistance, and IGF1 can enhance pancreatic β cell viability and inhibit apoptosis by activating the Sirt1/PI3K/Akt/FoxO1 pathway, inducing insulin secretion, and alleviating oxidative damage." (PMID 37701184, 2023). "Gluconeogenesis disorder is the most typical feature of insulin resistance in which HNF-4α synergizes with PGC-1α, FOXO1 and other key enzymes to induce gluconeogenesis, and Leptin regulates the AMPK pathway by inhibiting HNF-4α and promoting SIRT1 expression." (PMID 37705071, 2023). "The key mechanism of insulin resistance is dysfunction of the insulin signaling, while the IRS1/AKT/FOXO1 signaling pathway plays a vital role." (PMID 38034083, 2023).
Insulin resistance (continued). "In a previous study, Liu and co‐workers showed that quercetin and EGCG improved insulin resistance and hepatic gluconeogenesis via the IRS1/Akt/FOXO1 axis and involving miR‐27a‐3p and miR‐96–5p." (PMID 37329278, 2023). "In the liver, Notch signaling occurred in concordance with the transcription factor forkhead box protein O1 (FoxO1) via the Notch ICD, with Notch1 gain-of-function promoting insulin resistance and glucose-6-phosphatase expression in a FoxO1-dependent manner." (PMID 35330188, 2022). "It appears, therefore, that FOXO1 is a gatekeeper of a central crossroad between the most important proteolytic pathway (UPP) and insulin resistance." (PMID 34769017, 2021). "In the liver, excessive oxidation of circulating FFA hyperactivates pyruvate carboxylase activity and gluconeogenesis via FoxO1, while DAG increased levels reduce PI3K/AKT signaling to exacerbate insulin resistance." (PMID 34069890, 2021). "In these rats, because of insulin resistance, the PI3K/PDK1/PKB-FoxO1 regulatory axis was damaged, resulting in increasing the amount of FOXO1 protein and food intake." (PMID 31936903, 2020). "FOXO1 inhibition by AS1842856 suppresses adipogenesis and diminishes vascular insulin resistance in human obesity." (PMID 31591479, 2020). "PPARα was shown to bind to and antagonize FOXO1 in hepatic apoC-III expression, suggesting the importance of FOXO1 deregulation in the pathology of insulin resistance and hypertriglyceridemia." (PMID 32182991, 2020). "In fact, FOXO1 expression was greater in HIR-MO individuals in comparison with LIR-MO subjects, suggesting a possible relationship between FOXO1 and insulin resistance during adipocyte differentiation." (PMID 31547433, 2019). "Here, for the first time, we provide evidence demonstrating that spexin inhibits hepatic gluconeogenesis to alleviate insulin resistance in high-fat-diet (HFD)-induced rats and insulin-resistant cells via the FoxO1/PGC-1α pathway." (PMID 31853220, 2019). "We provide data that support the idea that C/EBP-α, FOXO1, PPAR-γ2 and IGFBP-2 in visceral adipose tissue are related to obesity-related insulin resistance." (PMID 31547433, 2019). "In insulin resistance, Akt level decreased and CREB, nuclear FoxO1 expression is increased and co-activated with PGC-1α, in turn regulates downstream target genes to promote gluconeogenesis." (PMID 31853220, 2019). "Data presented here demonstrate that Foxo1 and Foxo3 in CD4+ T cells likely act as a metabolic regulator that can suppress beiging with the potential capacity to accelerate obesity-induced insulin resistance." (PMID 31756626, 2019). "Thus, increased expression of FoXO1 may be a reason of aggravated insulin resistance." (PMID 31805951, 2019). "GRE showed a strong potential to ameliorate hepatic insulin resistance by improving insulin sensitivity through the regulation of PI3K/AKT, FOXO1 and AMPK-mediated pathways." (PMID 30717198, 2019). "FOXO1 is another member of FOXO gene family, which has a main function in glucose hemostasis and insulin resistance." (PMID 31565649, 2018). "Firstly, IRE1 activation prevents the inhibition of insulin signaling on forkhead box O1 (FOXO1) activation, thus induces gluconeogenesis, which is known as insulin resistance." (PMID 28777337, 2017). "Enhanced expression of FOXO1 downstream target gene PDK4 gene is also observed in high fat and obese animal models of insulin resistance, which adversely regulate insulin actions." (PMID 26956801, 2016). "In insulin resistance, the reduced activation of PI3K leads to increased forkhead box protein O1 (FOXO1) activation, which is normally inhibited by activated PI3K." (PMID 25725623, 2015). "Hepatic PGC1-alpha binds to and coactivates transcription factors such as HNF-4alfa and Foxo1, coordinating the expression of rate-limiting gluconeogenic genes (i.e. PEPCK and G6Pase) during insulin resistance." (PMID 26445495, 2015).
Insulin resistance (continued). "Conversely, we show that NRG1 can strongly phosphorylate AKT at Ser473 and FOXO1 at Ser256 in db/db mice, suggesting that the NRG1 pathway in liver is functional also in conditions of insulin resistance." (PMID 26230680, 2015). "Studies have shown that in the setting of insulin resistance, the activation of the AKT/FOXO1 signaling pathway is reduced; consequently, FOXO1 activity is enhanced, which promotes hepatic gluconeogenic gene expression, leading to increased blood glucose levels." (PMID 40313619, 2025). "Foxo1 liver ablation normalizes excessive glucose production and severe hepatic insulin resistance in animals lacking Akt1 and Akt2." (PMID 40141412, 2025). "However, in the setting of insulin resistance, the PI3K/AKT/FoxO1 pathway becomes inactive, leading to elevated FoxO1 activity, increased MSTN expression, and the subsequent development of skeletal complications associated with T2DM." (PMID 40136413, 2025). "ATM is involved in insulin resistance, TGF-beta, and FOXO1 pathways in the constructed interactome." (PMID 39457593, 2024). "Furthermore, inhibition of miR-721 in high-fat diet-induced insulin-resistant mice resulted in restoration of KDM2A levels, concomitantly reducing FOXO1, PCK1, and G6PC expression, attenuating gluconeogenesis, hyperglycemia, and improving glucose tolerance." (PMID 38745315, 2024). "In conclusion GDF-15 could have an adverse effect on sarcopenia and decrease skeletal muscle mass by activating FOXO1 and SMAD3, however, its protecting role against insulin resistance could reverse the process of sarcopenia." (PMID 38409184, 2024). "We first showed that candesartan and azilsartan could alleviate insulin resistance in PA-treated HepG2 cells by fully restoring the impaired insulin-stimulated phosphorylation of AKT and its downstream substrates GSK3β, AS160, FOXO1, and FOXO3." (PMID 37121975, 2023). "Therefore, PC-derived exosomal miRNAs were found to be capable of inducing the insulin resistance of skeletal muscle cells through insulin and PI3K/Akt/FoxO1 signalling pathways." (PMID 37373351, 2023). "The apoptosis of pancreatic β-cells is influenced by the initiation of the MAPK and FoxO1/PPAR signaling pathways and may accelerate the development of type II diabetes and insulin resistance." (PMID 37241737, 2023). "Adipose-specific knockdown of Sirtuin 6 increases the acetylated form of FoxO1 causing an decrease in FoxO1 activity and downregulation of ATGL, which results in adipocyte hypertrophy (without hyperplasia), and promotes insulin resistance in obese fed mice." (PMID 37941908, 2023). "Selenoprotein P hepatic transcription is regulated similarly to that of a gluconeogenic enzyme through transcription factors FoxO1 and HNF-4α together with the co-activator PGC-1α and may also become dysregulated in hyperglycemia and insulin-resistance states." (PMID 37895024, 2023). "Despite the FoxO1 central role in the progression of insulin resistance, the effect of FoxO1 on β cell function has not been explored in detail and remains somewhat conjectural." (PMID 35198097, 2022). "In addition, FoxO1 expression was stimulated by hepatitis C virus (HCV) infection to suppress the activation of Akt, which resulted in HCV-induced insulin resistance." (PMID 35057469, 2022). "Similarly, during insulin resistance, the hepatic AKT activity declines and that leads to both upregulation of forkhead box protein O1 (FOXO1) and promotion of gluconeogenesis, as well as to the diminution of glycogen synthesis." (PMID 34208379, 2021). "Overall, the present investigation demonstrates that calystegines from Hyoscyamus albus provide cytoprotection to the HepG2 cells against insulin/glucose induced insulin resistance and apoptosis due to the regulation of SIRT1/Foxo1/G6PC/mTOR and NF-κB/JNK/TLR4 signaling pathways." (PMID 34034759, 2021).
Insulin resistance (continued). "By upregulating secreted frizzled-related protein 4 (SFRP4)—an adipokine which increases insulin resistance by decreasing the abundance of insulin receptor substrate 1 (IRS1) and the FOXO1 transcription factor—these two miRNAs can aggravate insulin resistance in the course of human obesity." (PMID 34943849, 2021). "To verify that the reporter islets for β-cell insulin resistance in the ACE did, indeed, report the status of the endogenous islets of the animals, we analyzed FoxO1 localization by immunofluorescence in pancreatic islet sections from mice fed an HFHSD for 8 wk." (PMID 29957055, 2019). "Thus, FOXO1 is one of the crucial metabolic links between PPAR-γ and C/EBP-α, suggesting an interesting role that FOXO1 must play in adipogenesis and insulin resistance." (PMID 31547433, 2019). "Indeed, myeloid cell-specific Irs2-deficient mice show impairment of IL-4-induced M2a-subtype macrophage activation, as a result of stabilization of the FoxO1/HDAC3/NCoR1 corepressor complex, resulting in insulin resistance under the HF diet condition." (PMID 30451856, 2018). "Additionally, MAE improves hepatic insulin resistance through inhibiting PGC-1α and FOXO1 transcriptional activity to decrease gluconeogenesis as well as suppressing JNK phosphorylation to enhance insulin signalling transduction." (PMID 28713491, 2017). "Blocking signal transduction through insulin receptors led to an increase in nuclear FoxO1(H215R)GFP, i.e. an increase in insulin resistance in 35% of the analyzed cells, while blocking signalling via IGF1 receptors did not change the cytosolic localization of the biosensor." (PMID 26899548, 2016). "In vitro studies have shown that anthocyanins activate HepG2 cells by upregulating FOXO1 and PGC-1α expression, reducing phosphoenolpyruvate carboxykinase (PEPCK) and glucose-6-phosphatase (G6Pase) activity, thus decreasing gluconeogenesis and countering insulin resistance." (PMID 39928643, 2025). "In our hepatic insulin resistant mouse model (hepatic insulin receptor substrate 1 (IRS1) and IRS2 double knockout (DKO)), metformin action on glycemic control was impaired, which is largely improved by further deletion of hepatic TGF-β1 (TKObeta1) or hepatic Foxo1 (TKOfoxo1)." (PMID 38397103, 2024). "Additionally, we report that laccaic acid could attenuate insulin resistance and reduce gluconeogenesis via altering H3K36me2 methylation around the FOXO1 promoter by reducing the elevated miR721 and restoring KDM2A/FOXO1 axis." (PMID 38745315, 2024). "Therefore, it can be speculated that resveratrol can inhibit FOXO1 expression through SIRT1, thereby improving insulin resistance and restoring normal blood glucose levels." (PMID 35739982, 2022). "Dysregulated secretion of leptin and the increased expression of FoxO1 in propiomelanocortin (POMC) neurons provoke hyperphagia and obesity, as well as hypothalamic hyperactivation of mTORC1, seems to induce hepatic insulin resistance through the inhibition of IRS-1/AKT axis and K (ATP) channels." (PMID 34069890, 2021). "The mechanisms by which IL-1β mediates insulin-resistance have been attributed, at least in part, to downregulation of insulin substrate receptor-1 (IRS-1) and aberrant activity of the transcription factors NF-κB and FOXO1 (Forkhead box protein O1) during obesity or inflammatory conditions." (PMID 33178196, 2020). "In our model of insulin resistance, although ACC phosphorylation was slightly downregulated without significance, a marked increase in the expression of MCD was followed by reduced phosphorylation of FOXO1, as well as impaired AKT and AMPK expression after palmitate exposure." (PMID 30717198, 2019). "In hepatic insulin resistance, FoxO1 is no longer inhibited and SREBP-1 is active." (PMID 29587401, 2018). "However, because FOXO1 dysregulation must precede dysregulation of insulin control of MARCH1, this phenomenon is likely to be consequence rather than cause of insulin resistance." (PMID 27577745, 2016).